COMP (cartilage oligomeric matrix protein)
Description:
Plays a role in the structural integrity of cartilage via its interaction with other extracellular matrix proteins such as the collagens and fibronectin. Can mediate the interaction of chondrocytes with the cartilage extracellular matrix through interaction with cell surface integrin receptors. Could play a role in the pathogenesis of osteoarthritis. Potent suppressor of apoptosis in both primary chondrocytes and transformed cells. Suppresses apoptosis by blocking the activation of caspase-3 and by inducing the IAP family of survival proteins (BIRC3, BIRC2, BIRC5 and XIAP). Essential for maintaining a vascular smooth muscle cells (VSMCs) contractile/differentiated phenotype under physiological and pathological stimuli. Maintains this phenotype of VSMCs by interacting with ITGA7 (By similarity).
Synonyms: TSP5; MED; THBS5; TSP-5; CTS2; EDM1; EPD1; PSACH
Tractability: Antibody: UniProt places it where antibodies can reach, with high confidence; its Gene Ontology location is reachable by antibodies, with high confidence; UniProt predicts a signal peptide or a membrane-spanning region.
Gene: Protein-coding gene on chromosome 19 (18,782,773 to 18,791,305, reverse strand). Ensembl gene ENSG00000105664.
Subcellular location: Secreted, extracellular space, extracellular matrix
Subcellular location (Human Protein Atlas): Golgi apparatus; Predicted to be secreted
Pathways (Reactome):
Extracellular matrix organization: ECM proteoglycans; Integrin cell surface interactions
Gene Ontology:
Molecular function: calcium ion binding; collagen binding; heparan sulfate proteoglycan binding; heparin binding; protease binding; protein binding; proteoglycan binding; extracellular matrix structural constituent; BMP binding; integrin binding
Biological process: cartilage homeostasis; limb development; negative regulation of apoptotic process; protein homooligomerization; animal organ morphogenesis; skeletal system development; cell adhesion; collagen fibril organization
Cellular component: extracellular exosome; extracellular matrix; extracellular region; non-collagenous component of interstitial matrix; thrombospondin complex; protein-containing complex
Genetic constraint (gnomAD): Loss-of-function variants: 80 observed, 89.82 expected, observed/expected ratio (o/e) 0.89, 90% interval 0.74 to 1.07. The upper end of that interval is the gene's LOEUF score, 1.07, which puts it in group 4 of 6, group 1 being the genes least tolerant of losing a copy. Missense variants: 905 observed, 1,038.4 expected, observed/expected ratio (o/e) 0.87, 90% interval 0.82 to 0.92. Synonymous variants: 438 observed, 425.81 expected, observed/expected ratio (o/e) 1.03, 90% interval 0.95 to 1.11.
Gene-disease validity (ClinGen):
ClinGen rates the evidence that COMP causes each of these diseases.
COMP-related skeletal dysplasia (autosomal dominant): Definitive. Any skeletal disorder in which the cause of the disease is a variant in the COMP gene.
Homologues: Orthologues: chimpanzee COMP (99% identical), macaque COMP (98% identical), pig COMP (93% identical), dog COMP (93% identical), guinea pig COMP (91% identical), mouse Comp (91% identical), rat Comp (89% identical), zebrafish comp (68% identical), Drosophila melanogaster Tsp (49% identical). Paralogues in human: THBS4 (69% identical), THBS3 (64% identical), THBS2 (49% identical), THBS1 (49% identical), ISM1 (8% identical).
Diseases named in the same sentence as COMP in open-access papers:
COMP is named in the same sentence as 225 diseases in open-access papers, as found by Europe PMC text mining. Sharing a sentence is not in itself a finding about the gene and the disease. The quoted sentences say what the papers report.
osteoarthritis (93 papers, 2006 to 2026). A noninflammatory degenerative joint disease occurring chiefly in older persons, characterized by degeneration of the articular cartilage, hypertrophy of bone at the margins and changes in the synovial membrane. "COMP is widely associated with multiple diseases and can act as a biomarker for osteoarthritis (OA), rheumatoid arthritis (RA), intervertebral disc degeneration (IVDD), and psoriatic arthritis." (PMID 41009743, 2025). "Upregulated metalloproteinase activity leads to COMP degradation, a hallmark of degenerative joint diseases such as OA." (PMID 39672391, 2025). "This is confirmed by the IHC reaction for COMP, a biomarker for cartilage degeneration, associated with osteoarthritis and rheumatoid arthritis." (PMID 38396667, 2024). "Osteoarthritis (OA) is increasing worldwide, and previous work found that OA increases systemic cartilage oligomeric matrix protein (COMP), which has also been implicated in prostate cancer (PCa)." (PMID 38892202, 2024). "The COMP pathogenic variant p.N453fs*62 segregated with short stature or low-normal height and early-onset osteoarthritis in the three-generation pedigree." (PMID 39415983, 2024). "COMP is associated with different diseases and it is a well-known biomarker for pathologies that elicit cartilage destruction such as osteoarthritis, rheumatoid arthritis, intervertebral disc degeneration, and psoriatic arthritis." (PMID 36835076, 2023). "COMP is often used as a biomarker to track the progression of osteoarthritis, and COMP elevations are associated with the formation of knee osteophytes and joint space narrowing." (PMID 38655158, 2022). "This article suggests that this mutation of COMP is not only causal for idiopathic early-onset osteoarthritis or severe MED, but can also be associated to a broad phenotypic variability with always joint alterations." (PMID 34680093, 2021). "Nevertheless, osteoarthritis is known to be associated with an enhanced risk for long-term cardiovascular diseases and COMP is expressed in vascular smooth muscle cells as well as cardiomyocytes and implicated in cardiovascular pathology." (PMID 31963737, 2020). "Cartilage damage associated with rheumatoid arthritis and osteoarthritis have been associated with changes in COMP expression." (PMID 28114331, 2017). "ADAMTS-12's involvements in osteoarthritis is most probably due to its association and degradation of cartilage oligomeric matrix protein (COMP)." (PMID 24876675, 2014). "Patients with the COMP mutation have characteristics of marked alterations of hip joints leading to severe osteoarthritis in early childhood." (PMID 25381065, 2014). "Pseudoachondroplasia (PSACH) and multiple epiphyseal dysplasia (MED) are skeletal disorders resulting from mutations in COMP, matrilin-3 or collagen IX and are characterised by short-limbed dwarfism and premature osteoarthritis." (PMID 24312420, 2013). "In clinical practice, COMP is used as a prognostic marker for joint injury, a biomarker for idiopathic pulmonary fibrosis, and a biomarker for cartilage degeneration-associated osteoarthritis and rheumatoid arthritis." (PMID 37082197, 2023). "This exploratory analysis gives an idea of specific pathogenetic pathways or phenotypes that might be associated with COMP and should be further considered, i.e., as potential confounders in osteoarthritis cohorts." (PMID 31963737, 2020). "For SPP1, also known as osteopontin, it has been indicated that it causes a decrease of collagen 2 and COMP in chondrocytes from osteoarthritis, but in OA progression, it plays an important role as a regulator, and it has been identified as a susceptibility gene for RA." (PMID 32434555, 2020). "We supposed that the mutant COMP may be retained in the chondrocyte and cause increasing rER stress and cells death and then result in chondrocyte dysplasia and osteoarthritis." (PMID 29104872, 2017).
osteoarthritis (continued). "Both of these proteins have recently been proposed to contribute to TGFβ1 signaling in early cartilage development and alterations within TGFβ1 signaling have been linked to osteoarthritis, whilst COMP itself has recently been identified as a TGFβ-responsive gene." (PMID 23951406, 2013). "Furthermore, pseudoachondroplasia, a genetic pathology caused by a mutation on the protein COMP (Cartilage Oligo Matrix Protein) is characterised by abnormal joint architecture, joint erosion and osteoarthritis." (PMID 23840483, 2013). "Furthermore, COMP has been shown to be upregulated after traumatic knee injury and has been implicated in the pathogenesis of rheumatoid arthritis and osteoarthritis (OA)." (PMID 16542502, 2006). "High values of COMP measured in a standardized protocol with a sufficient resting period before drawing blood can be interpreted as an indicator for changes in extracellular matrix metabolism, but also as a risk factor for degenerative joint diseases like osteoarthritis." (PMID 32982779, 2020). "This study aimed to assess associations between serum cartilage oligomeric matrix protein (sCOMP) and phenotypic characteristics in late-stage hip and knee Osteoarthritis (OA) as well as its correlation with further serum markers of possible comorbidities in the Ulm Osteoarthritis Study." (PMID 31963737, 2020). "A combinatorial algorithm utilizing cartilage oligomeric matrix protein, and Interleukin‐8 concentrations was developed that differentiated primary osteoarthritis from inflammatory arthritis." (PMID 39690934, 2025). "The practical utility of the platform was demonstrated through real-time, parallel monitoring of antigen–antibody interactions and the specific detection of the osteoarthritis biomarker COMP in human synovial fluid." (PMID 41516471, 2025). "The ADAMTS7 gene, also referred to as COMP-ADAMTSs due to its role in degrading cartilage oligomeric matrix protein (COMP), has been found to be significantly elevated in conditions such as osteoarthritis and rheumatoid arthritis." (PMID 40564318, 2025). "For instance, decreased serum levels of COMP have been observed in patients with severe COVID-19, suggesting a potential link to cartilage degradation and osteoarthritis progression." (PMID 40943488, 2025). "(A) Discovery data demonstrating the utility of COMP and IL‐8 as a dual biomarker algorithm in differentiating osteoarthritis from other arthropathies." (PMID 39690934, 2025). "ADAMTS7 is also involved in the progression of osteoarthritis since it promotes the breakdown of cartilage oligomeric matrix protein (COMP)." (PMID 41296055, 2025). "COMP has previously been shown to be a marker of cartilage breakdown, and therefore a driver of disease pathogenesis in osteoarthritis knees." (PMID 38403470, 2024). "We quantified the levels of biomarkers of cartilage and bone anabolism (CPII and N-MID) and catabolism (CTX-I and CTX-II), as well as of osteoarthritis (HA and COMP) and inflammation (IL-6 and PGE2)." (PMID 38069100, 2023). "The cited authors showed that ADAMTS group enzymes, namely ADAMTS7 and ADAMTS12, are overexpressed in cartilage and synovial membrane in osteoarthritis patients, contributing to COMP degradation." (PMID 36079004, 2022). "In conclusion, this study has succinctly demonstrated that PN-G is capable of relieving the clinical symptoms of osteoarthritis, which is measurable through the established osteoarthritic serum biomarker, Cartilage Oligomeric Matrix Protein (COMP)." (PMID 35600853, 2022). "Cartilage Oligomeric Matrix Protein (COMP) is a biomarker of arthritis, including osteoarthritis, particularly, knee osteoarthritis." (PMID 35600853, 2022). "COMP is significantly upregulated in the early stages of osteoarthritis, in an apparent attempt to repair the cartilage; and, since it is a cartilage turnover marker, it also increases concomitantly in people with early stages of osteoarthritis." (PMID 34948030, 2021).
osteoarthritis (continued). "The investigation of COMP in the sera of patients was performed first in patients with rheumatoid arthritis and osteoarthritis in an attempt to evaluate the destruction of the cartilage." (PMID 34298722, 2021). "In our study, in contrast to the clinical use of COMP as a biomarker of osteoarthritis, the acute response of COMP to mechanical loading was analyzed." (PMID 32982779, 2020). "In humans, chondrodysplasia-causing mutations in COMP, collagen IX, or MATN3 are frequently associated with premature osteoarthritis." (PMID 31963938, 2020). "Cartilage Oligomeric Matrix Protein (COMP) has been used as a molecular marker for osteoarthritis in humans and horses but assays for the protein in tendon sheath synovial fluids have shown overlap between horses affected by tendinopathy and controls." (PMID 32245107, 2020). "For example, concentrations of COMP are generally elevated among individuals with osteoarthritis or joint injury compared to healthy individuals." (PMID 31650307, 2019). "Currently, studies of both acute and chronic exercise have been limited to COMP; however, other promising biomarkers exist, including a number that have been identified as biomarkers of osteoarthritis." (PMID 31650307, 2019). "IHC demonstrated that those with osteoarthritis, had greater expression of COMP in the prostate samples (mean 23.9% vs 5.84%, p<0.05) but not of Ki-67, CD31, or PSMA." (PMID 31413818, 2019). "The current study evaluated the influence of osteoarthritis and subsequent upregulation of COMP on the prostate cancer presentation and disease progression." (PMID 31413818, 2019). "COMP is found in human chondrocytes and is known to increase after knee injury and in early stages of osteoarthritis and COMP levels have been shown to increase in endurance-trained runners." (PMID 30696041, 2019). "Patients with osteoarthritis expressed higher COMP levels in the prostate tissue and most likely in distant lymphatic nodes." (PMID 31413818, 2019). "Although rheumatoid arthritis has a different pathophysiology from osteoarthritis, it leads to chronic joint damage that can stimulate COMP production and secretion into the blood stream." (PMID 31413818, 2019). "COMP fragments are released into the joint fluid following injury and during the early stages of osteoarthritis, and therefore, COMP is considered a marker for cartilage degradation." (PMID 31665048, 2019). "Nonetheless, this is the first report of this relationship, and future studies are needed to evaluate systemic levels of COMP and possible temporal changes in COMP expression to further examine the interaction between osteoarthritis and prostate cancer." (PMID 31413818, 2019). "In the prostate samples, COMP expression was significantly greater in patients with osteoarthritis (mean 23.9% vs 5.85%, p<0.05)." (PMID 31413818, 2019). "In that study, 42 women with osteoarthritis in different stages were treated with a well-rounded exercise program over a period of 12 weeks leading to a significant increase of plasma COMP." (PMID 30188931, 2018). "Cartilage oligomeric matrix protein (COMP) as potential prognostic marker for osteoarthritis was also measured in serum, as were vitamin D levels." (PMID 30515164, 2018). "COMP was suggested as biomarker for disease progression of rheumatoid arthritis, osteoarthritis and liver fibrosis, and early cartilage lesions in the knee." (PMID 30188931, 2018). "The serum COMP levels were stable during the daytime in patients with osteoarthritis and in those with rheumatoid arthritis." (PMID 30180854, 2018). "Serum levels of COMP in patients with osteoarthritis (OA) and rheumatoid arthritis (RA) were elevated." (PMID 30180854, 2018). "Elevated levels of COMP are released during erosive joint disease such as rheumatoid arthritis and osteoarthritis." (PMID 29166937, 2017).
osteoarthritis (continued). "Overexpression of ADAMTS-7 gene promotes the breakdown of cartilage oligomeric matrix protein (COMP) matrix and accelerates the progression of both surgically induced osteoarthritis and collagen-induced arthritis." (PMID 26696755, 2015). "Pseudoachondroplasia (PSACH) is an autosomal dominant skeletal dysplasia caused by mutations in cartilage oligomeric matrix protein (COMP) and characterised by short limbed dwarfism and early onset osteoarthritis." (PMID 24558358, 2014). "In contrary, COMP levels are increased in patients with rheumatoid arthritis (RA) and the molecule has been proposed as a potential biomarker for RA and osteoarthritis (OA) activity." (PMID 24376648, 2013). "COMP is a structural component of cartilage, and it has been shown to be released during erosive joint diseases such as RA and osteoarthritis (OA)." (PMID 22264230, 2012). "Cartilage oligomeric matrix protein (COMP) is found at elevated concentrations in sera of patients with joint diseases such as rheumatoid arthritis (RA) and osteoarthritis (OA)." (PMID 22264230, 2012). "Serum and synovial levels of COMP are now used to assess cartilage erosion in osteoarthritis and joint injury." (PMID 20421976, 2010). "COMP (Cartilage oligomeric matrix protein) is a matrix protein, which is currently studied as a potential serum marker for cartilage processes in osteoarthritis (OA)." (PMID 17156423, 2006). "With the help of immunohistochemistry, Western blot, in situ hybridization, and real-time reverse transcription-polymerase chain reaction, we aimed to elucidate the role of COMP in human embryonic, adult healthy, and osteoarthritis (OA) cartilage tissue." (PMID 16542502, 2006). "Therefore, a combinatorial algorithm using cartilage oligomeric matrix protein and Interleukin‐8 concentrations was developed to differentiate primary osteoarthritis from inflammatory arthritis." (PMID 39690934, 2025). "This review covers the roles of cartilage oligomeric matrix protein (COMP), an established biomarker of cartilage breakdown in pathological tissues in osteoarthritis, and in emerging areas in extracellular matrix and vascular remodeling associated with trauma, fibrosis and cancer." (PMID 41009743, 2025). "Studies on osteoarthritis have acknowledged a sensitivity of COMP to mechanical loading." (PMID 40410839, 2025). "Their findings revealed a significantly greater increase in COMP levels in post-COVID-19 osteoarthritis patients compared to those with primary knee osteoarthritis, suggesting a potential exacerbating effect of SARS-CoV-2 on cartilage metabolism and joint pathology." (PMID 40943488, 2025). "Additionally, a case report described a patient with osteoarthritis who had serum COMP levels twice higher than average." (PMID 38563861, 2024). "Considering these data, lower physical activity related to pain in knee OA may explain lower COMP levels in osteoarthritis patients." (PMID 38791302, 2024). "Thus, biomarkers of bone anabolism (N-MID) and catabolism (CTX-I), cartilage anabolism (CPII) and catabolism (CTX-II), and osteoarthritis (COMP and HA) were quantified from birth to 33 months using blood samples collected from both groups of castrated horses." (PMID 38069100, 2023). "The results demonstrated that miR-92a was downregulated in equine synovial fluid from horses with severe osteoarthritis and there was a significant increase in COMP, COL1A2, RUNX2 and SOX9 following miR-92a mimic treatment of equine chondrocytes in monolayer culture." (PMID 36555166, 2022). "Moreover, accumulating evidence supports the links between COMP and other skeleton diseases, such as osteoarthritis (OA) and rheumatoid arthritis (RA)." (PMID 36012514, 2022). "The roles of COMP in other skeleton diseases, such as osteoarthritis, have been implied." (PMID 36012514, 2022). "Furthermore, COMP fragments observed in cartilage explants of osteoarthritis patients showed similar size to those identified from in vitro studies." (PMID 33996918, 2021).